GLI3 (GLI family zinc finger 3)
Diseases named in the same sentence as GLI3 in open-access papers (continued):
Sharing a sentence is not in itself a finding about the gene and the disease.
tumor (continued). "Strikingly, co-injection of tumor cells with Gli1/Gli2/Gli3 KO fibroblasts promotes tumor growth to the same degree as parental Gli1 KO fibroblasts and WT control fibroblasts." (PMID 35867772, 2022). "To study the role of Gli1/Gli2/Gli3 in tumor growth, we performed tumor implantation experiments with Gli KO pancreatic fibroblasts." (PMID 35867772, 2022). "Conversely, antagonizing GLI targets in tumor cells either by knocking down Gli1 or over-expressing a constitutive GLI3 repressor increases tumor cell death and reduces colony formation." (PMID 35867772, 2022). "In contrast, Gli1/Gli2/Gli3 KO fibroblasts recruit MDSCs and exclude NK cells, leading to sustained tumor growth." (PMID 35867772, 2022). "We therefore suspected that in the absence of T cells, the enhanced NK cell recruitment in our Gli2/Gli3 KO condition was responsible for antagonizing tumor growth." (PMID 35867772, 2022). "Given the detrimental effects observed when Gli1, Gli2, and Gli3 are deleted at PanIN stages, we next tested how Gli1/Gli2/Gli3 KO fibroblasts impact invasive tumor growth." (PMID 35867772, 2022). "To assess which types of macrophages are impacted by the loss of Gli2/Gli3, we evaluated the expression of arginase 1 (ARG1), a marker of immunosuppressive tumor-associated macrophages (TAMs)." (PMID 35867772, 2022). "In contrast, depleting NK cells in tumors co-injected with Gli2/Gli3 KO fibroblasts rescues tumor growth, and the resulting tumors are equivalent in size to tumors co-injected with WT fibroblasts." (PMID 35867772, 2022). "In invasive tumors, Gli2/Gli3 KO fibroblasts exclude immunosuppressive myeloid cells and suppress tumor growth by recruiting natural killer cells." (PMID 35867772, 2022). "The regressive tumor WT01 carried GLI3 Q1437*, the triphasic WT02 harbored MAX R60Q and MYCN T58M mutations, and the blastemal WT03 showed a heterozygous DIS3L2 deletion and a STK32C V339M mutation." (PMID 31562394, 2020). "Reports suggesting GLI3’s tumor suppressive role have been rare but raise the question where the contradictory attributes of GLI3 in cancer come from." (PMID 32245491, 2020). "Although these studies are infrequent, this raises the question of how GLI3 can act as both a tumor initiator and tumor suppressor." (PMID 32245491, 2020). "Overall, higher epithelial GLI3 expression in the tumor was shown to be an independent marker of a favorable prognosis." (PMID 28877722, 2017). "When considering Hh signaling proteins in the epithelium, we observed that low levels of PTCH1 and GLI3 expression were more likely to occur in tumor tissue than in benign (PTCH1 76% PCa versus 26.6% benign, and GLI3 55.2% versus 29%, respectively, p < 0.001)." (PMID 28877722, 2017). "We correlated the high or low expression of GLI1/GLI3/pathway molecules in the tumor with cancer relapse." (PMID 28413604, 2017). "The Hh signaling pathway appeared to be more active in PCa than in benign prostate tissue, as demonstrated by lower expression of the negative regulators PTCH1 and GLI3 in the tumor tissue compared to benign." (PMID 28877722, 2017). "We investigated expression differences of miR-378a-3p and gli3 between tumour and non-tumour liver tissues from patients with HCC and severe fibrosis." (PMID 27001906, 2016). "There was also elevated mRNA expression of Shh-signaling pathway genes Gli1, Gli2, Gli3 and Ptch1/2 in both tumor-adjacent skin and BCCs of IR-irradiated mice." (PMID 26413810, 2015). "Investigation on GLI3 expression in tumor samples has been rare, and the possible clinical impact of GLI3 expression raised by our study needs further corroboration by additional research studies." (PMID 25103784, 2014). "Additionally, GLI2 and GLI3 displayed a significant positive correlation in 9 of the examined tumor cell lines." (PMID 38498906, 2024). "Therefore, SPO and GSK3β are probably involved in downregulation or degradation of GLI3 and promotes tumor aggressiveness in PCa tissues." (PMID 38370352, 2024).
tumor (continued). "Moreover, GLI1, GLI2, and GLI3 were significantly expressed in ten, ten, and thirteen tumor stages, respectively, suggesting their involvement in tumor progression." (PMID 38498906, 2024). "GLI3, a member of the Hedgehog signaling pathway, is upregulated in a variety of tumor types." (PMID 36959801, 2023). "Since both SETD7 and GLI1 mRNA levels were upregulated in A-549 cell line when compared to the non-malignant bronchial epithelial lung cell line BEAS-2B, it is likely that SETD7 activates the SHH signalling in LCa promoting tumour growth and metastasis in vitro and in vivo via GLI3 methylation." (PMID 35326563, 2022). "We next wanted to determine why Gli2/Gli3 KO fibroblasts fail to promote tumor growth." (PMID 35867772, 2022). "We were surprised to find that total myeloid cells and macrophages do not change following the loss of Gli2/Gli3 in our tumor implantation experiments, in contrast to our KF;Gli2/Gli3 cKO model." (PMID 35867772, 2022). "In other studies, ARNT2, CREB3L1, GLI3, and PBX3 have been associated with tumor progression." (PMID 33924679, 2021). "Additionally, A549 xenografts in mice, expressing GLI3-FL with mutations in SET7 methylation sites, showed less migration, invasiveness and decreased tumor volume in comparison to mice injected with A549 xenografts expressing WT GLI3." (PMID 32245491, 2020). "In addition, a significant reduction in proliferation and invasion was observed in vitro and a positive correlation between GLI3 expression and tumor size was confirmed in vivo." (PMID 32245491, 2020). "In some tumor cell lines, expression of GLI3 was lower (DOR, Saos-2, and H-196)." (PMID 30201866, 2018). "Our present study indicates that Set7 mediated Gli3 methylation is critical for this oncogenic role of Shh pathway because cancer cells expressing Gli3K436R, Gli3K595R or Gli3KRKR showed severely reduced growth and metastasis in xenograft tumor models." (PMID 27146893, 2016). "Finally, functional experiments indicated that this Set7-mediated Gli3 methylation contributes to the tumor growth and metastasis in NSCLCs in vitro and in vivo." (PMID 27146893, 2016). "Since Set7 can augment Shh activation by increasing Gli3 stability and its DNA binding ability on the promoter regions of Gli1, we then determined whether this Set7-Gli3-Gli1 axis plays a role in tumor development." (PMID 27146893, 2016). "Since GLI-3 over-expression reduced tumor cell proliferation and induced apoptosis in colon CSCs, the GLI-3 induction by Bozepinib could be one of the mechanisms by which this drug exerts its anti-tumor activity in colon CSCs that must be deeply explored." (PMID 24946763, 2014). "One explanation for normal development in absence of PC is that there may be a constant level of Hh signal activation in the mammary gland that is continuously repressed by Gli3 to allow normal development and prevent tumor formation." (PMID 24594320, 2014). "The bifunctional nature of Ci, and of the mammalian homologues Gli2 and Gli3, could fulfil oncogenic or tumour suppressor roles in function of the status of the Hh signalling." (PMID 23667323, 2013). "Finally, GLI2 and GLI3 exhibited a significant positive correlation in 29 tumor tissues." (PMID 38498906, 2024). "We next assessed whether Gli2/Gli3 KO fibroblasts impacted the growth of tumor cells directly." (PMID 35867772, 2022). "The persistence of clonal mutations in ATM, PTK2, GLI3 and CLTCL1 in all tumour locations analysed in samples from diagnosis and at relapse in patient CB1002 could indicate the relevance of these SNVs for tumour progression." (PMID 34815394, 2021). "Thus, the purpose of this work was to evaluate the antitumoral activity of GANT61, a downstream inhibitor of the HH pathway, on the gene and protein expression of HH pathway components (PTCH1, GLI1, GLI2, and GLI3), as well as tumor cell proliferation and death in a metastatic OSCC cell line." (PMID 32846867, 2020).
tumor (continued). "Additionally, GLI3 regulates cell survival and invasion and correlates with tumor size in vivo." (PMID 32245491, 2020). "In addition to epigenetic modifications that suppress GLI3 tumor function, it might also be that a disruption of GLI3-FL/GLI3-R equilibrium within the cell leads to a cancerous phenotype and tumor growth." (PMID 32245491, 2020). "The two-group comparison—tumor/normal—showed, interestingly, a tumorous downregulation of the expression levels of GLI2 and GLI3." (PMID 40565349, 2025). "To assess the impact of GLI3 on tumor growth in vivo, we established a xenograft mouse model using HGC-27 and GT38 cells transduced with GLI3-specific or control sgRNAs." (PMID 39998882, 2025). "Our staining results of 190 samples show that expression of GLI1, GLI3, KRT16, and S100A7 was mostly detected in the epidermal layer overlying or bordering the tumor mass." (PMID 38892279, 2024). "Analysis of paired tumor and normal tissue samples from the TCGA database further verified significant expression of GLI1, GLI2, and GLI3 in nine, ten, and ten types of tumors, respectively." (PMID 38498906, 2024). "Regarding tumor tissues, TGCT, MESO, and SKCM exhibited the highest levels of GLI1, GLI2, and GLI3, respectively." (PMID 38498906, 2024). "Combining data from TCGA tumor samples and normal tissues from the GETx database showed significant expression of GLI1, GLI2, and GLI3 in 24, 28, and 23 types of cancer, respectively." (PMID 38498906, 2024). "The tumor mass itself was found positive for GLI1 and GLI3 in a proportion of samples, while S100A7 and KRT16 were rarely detected." (PMID 38892279, 2024). "In contrast, the expressions of SOCS1, EPS15, GLI3, NR2F2, and RCOR1 were significantly decreased in tumor compared to normal tissue (p < 0.05)." (PMID 37916165, 2023). "It was found that TERT‐induced miR500A mediated the down‐regulation of PTCH1, GLI3 and CUL3, while miR500A directly targets the 3′UTR of PTCH1, promoting tumour invasiveness." (PMID 33713376, 2021). "In both tumour and normal vulval epithelium, expression of SHH ligand was localised to the cytosol; PTCH1 to the membrane, cytosol and nucleus; and GLI1, GLI2 and GLI3 to the cytosol and nucleus." (PMID 34480080, 2021). "In this study, the oncogenic role of GLI3 in solid tumors was further validated when GLI3-FL-overexpressing DLD-1 and HT29 mouse xenografts showed significantly increased tumor formation compared to control cells." (PMID 32245491, 2020). "To explore the role of the GLI family proteins (include Gli1, Gli2, Gli3) in the onset and development of HCC, we examine tumor and matched adjacent normal tissue samples from 10 patients with HCC." (PMID 31616295, 2019). "The human tumor data paralleled our cell line findings in that there was high PTCH1, SMO, GLI2, and GLI3 mRNA, but low GLI1 mRNA." (PMID 27793025, 2016). "Expression of GLI1 and GLI3 mRNA was strongly correlated, and their overexpression, especially that of GLI1, was found to be predictive of aggressive tumor behavior." (PMID 25103784, 2014). "Interestingly, most of the positive staining was detected in the epidermis overlying or bordering the tumor mass, while the tumor mass had strong staining only in a smaller proportion of samples for GLI1 and GLI3." (PMID 38892279, 2024). "Similar analyses carried out on tumor cell lines indicated that GLI1 and GLI2 were significantly positively correlated in 15 of the tested cell lines, while GLI1 and GLI3 exhibited significant positive correlations in 6 cell lines, but a negative correlation in 1 cell line." (PMID 38498906, 2024).
tumor (continued). "Among these genes, PKM, CAV1, GLI3, PICK1, PRPF6, and UBE3A have been identified as oncogenes, and play a pivotal role in orchestrating tumor-host interactions, fostering tumor growth, promoting metastasis, enhancing resistance to therapy, and ensuring cellular survival." (PMID 38280969, 2024). "We observed increased 5hmC levels in H3K4me3 regions in genes relating to cell proliferation, such as CDK6 and ZMYND8, and reduced 5hmC levels in H3K4me3 regions in genes that may be related to tumor suppression, such as ARHGAP26 and GLI3." (PMID 37372359, 2023). "TdTomato expression was detected by IF in tumors from our Gli2/Gli3 KO fibroblast condition, confirming that the decrease in tumor growth was not simply due to the death of injected fibroblasts." (PMID 35867772, 2022). "In contrast, co-injecting Gli2/Gli3 KO fibroblasts with tumor cells fails to promote tumor growth, and produces tumors that are significantly smaller than tumors co-injected with WT fibroblasts." (PMID 35867772, 2022). "Although expression of the negative Hh pathway regulator, GLI3, was higher in normal vulval epithelium compared to that in the tumour, this was not statistically significant." (PMID 34480080, 2021). "Four variants [c.1393G>C (p.Gly465Arg) and c.2179G>A (p.Gly727Arg) in GLI3, c.360C>T (p.Ala120=) in CDKN2B and c.2794G>A (p.Val932Met) in PALB2] were identified in tumours that developed recurrence and in all cases were present both in primary and recurrent samples." (PMID 30344923, 2018). "The level of miR-378a-3p was lower in tumour tissues (0.82±0.185) than in non-tumour tissues (2.90±0.614), whereas gli3 mRNA level was higher in tumour tissues (6.98±1.991) than in non-tumour tissues (0.76±0.222)." (PMID 27001906, 2016). "Independent of tumor characteristics, such as histology and grades, higher expressions of SHH, PTCH1, PTCH2, and GLI1 have shown beneficial prognostic influence, whereas GLI2, GLI3, and SUFU are correlated with adverse clinical outcomes in OC patients." (PMID 40565349, 2025). "However, our RNA-seq analysis revealed that it was not GLI1 but rather GLI2 and GLI3 that were activated in paclitaxel-resistant NSCLC cells, potentially due to alterations in the tumor microenvironment." (PMID 38228910, 2024).
cancer (58 papers, 2009 to 2025). A tumor composed of atypical neoplastic, often pleomorphic cells that invade other tissues. "Abnormalities in GLI3 function are associated with the occurrence and development of various developmental diseases and cancers." (PMID 41142227, 2025). "Univariate Cox analysis for overall survival (OS) demonstrated that GLI1, GLI2, and GLI3 were risk factors for patients with 12, 8, and 6 types of cancer, respectively." (PMID 38498906, 2024). "PBX3 is well described as associated with poor prognostic in several cancer types, and the same is correct for GLI3." (PMID 33924679, 2021). "In cancer, GLI3’s behavior seems to be bipolar since it was linked to cancer promoting and inhibitory effect in cells which can be explained by GLI3-FL activator and GLI3-R inhibitory function in gene expression." (PMID 32245491, 2020). "SUFU and GLI3 have been linked to Hedgehog signaling, another pathway in cancer, suggesting a putative explanation for the link between TGF-β and Hedgehog signaling." (PMID 27096930, 2016). "Gli3 has been implicated in the growth and metastasis of several cancer types." (PMID 41018112, 2025). "Additionally, univariate Cox analysis of disease-specific survival (DSS) revealed that GLI1, GLI2, and GLI3 were risk factors for patients with 10, 7, and 5 types of cancer, respectively." (PMID 38498906, 2024). "Similarly, GLI1, GLI2, and GLI3 were identified as prognostic risk factors for patients with 9, 8, and 6 types of cancer, respectively, using progression-free interval (PFI) analyses." (PMID 38498906, 2024). "The depletion of GLI3 results in a reduction of cancer-related phenotypes, similar to those observed following USP47 knockdown." (PMID 39998882, 2025). "GLI3, which has been previously shown to be highly expressed in cancer stem-like populations, was especially responsive in co-culture, reinforcing the regulatory influence of astrocyte-derived cues." (PMID 40894044, 2025). "The same pathway includes GLI3, which was upregulated in Cond 2, and the relationship between the gene and Oct4, as well as morphological changes, were suggested to be present in cancer stem cells." (PMID 38977828, 2024). "GSEA analysis identified mechanisms associated with GLI1, GLI2, GLI3, and GLI1/2/3 gene sets in different cancers, where they were primarily linked to EMT activation." (PMID 38498906, 2024). "GLI3 is a member of the hedgehog (HH) signaling pathway, where it plays a role in embryonic development and in cancer." (PMID 39684827, 2024). "GLI3 is a transcription factor involved in the Hedgehog signaling pathway, and it plays an important role in development, immune system, and cancer." (PMID 36619306, 2022). "These evidences demonstrated that GLI3 was involved in the regulation of malignant process in different cancer types." (PMID 33506047, 2021). "These evidences suggested that GLI3 was involved in the malignant progression in different cancer types." (PMID 33506047, 2021). "Recently, accumulating studies have demonstrated that another GLI family member GLI3 was significantly upregulated in many human cancers." (PMID 33506047, 2021). "Further characterization of the biological role of GLI3 in these cancers will enhance our understanding of the biological significance of GLI3." (PMID 32245491, 2020). "GLI3 regulates various biological processes that are important for cancer cell growth and progression." (PMID 32245491, 2020). "In the current study, we have developed a qRT-PCR method to accurately determine the expression levels of SMO, PTCH1, GLI1, GLI2, and GLI3 in a panel of cancer cell lines." (PMID 32784501, 2020).